TNF (tumor necrosis factor)
Diseases named in the same sentence as TNF in open-access papers (continued):
Sharing a sentence is not in itself a finding about the gene and the disease.
breast carcinoma (1,447 papers, 1989 to 2026). "Curiously, TNF-α was correlated with NF-kB, and this association was linked to tumor size and stage in breast cancer tissue." (PMID 40481981, 2025). "Cytokines such as IL-6 and TNF-alpha have been consistently associated with lower overall survival and unfavorable response in women with breast cancer." (PMID 40558287, 2025). "Literature has reported that higher-intensity AE is linked to lowered levels of CRP, IL-6, and TNF-α, and this has been determined in breast cancer." (PMID 41480347, 2025). "The results showed significant associations, with both PCNA and TNF-α exhibiting a higher expression in the basal subtype of breast cancer (p < 0.05)." (PMID 40430573, 2025). "In the context of breast cancer survivors, exercise-mediated reductions in proinflammatory biomarkers such as IL-6, TNF-α, and CRP have been linked with lower mortality, reduced recurrence risk, and lower hospitalization rates." (PMID 41303335, 2025). "While TNF-α is recognised to be of some benefit in CC through its proapoptotic role, some evidence has linked SNPs in the TNF-α promoter genes with CC and other solid tumours such as breast cancer in various racial populations." (PMID 40259899, 2025). "In conclusion, IL-6 and TNF-alpha emerge as prognostic inflammatory biomarkers in women with breast cancer and are associated with poor survival and poor treatment response." (PMID 40558287, 2025). "For instance, IL-6 plays a central role in inflammation, autoimmunity, cancer, and age-related pathologies, primarily via the IL-6/STAT3 signaling pathway, and elevated levels of TNF-α have been associated with breast cancer recurrence." (PMID 41155372, 2025). "Specifically, we observed significant associations between CXCL8 and TNF-α genes in breast cancer cell lines." (PMID 40833805, 2025). "Gut bacteria, such as Lactobacillus, Bifidobacterium, and Streptococcus, are known to inhibit the production of pro-inflammatory cytokine TNF-α, which is associated with breast cancer growth and metastasis." (PMID 39994329, 2025). "EMT is a key event in cancer metastasis, and the observation that TNF EVs can induce EMT-associated morphological changes in MCF-7 cells highlights the potential role of EVs in driving metastasis in breast cancer." (PMID 40567500, 2025). "It has been associated with reduced interleukin-6 and tumor necrosis factor-α levels and anti-tumor activity in breast cancer xenograft models." (PMID 40731923, 2025). "Elevated levels of inflammatory markers, such as Tumor Necrosis Factor-α (TNF-α), Interleukin-6 (IL-6), and neutrophils, have been observed in HR-positive breast cancer patients, suggesting their potential role as diagnostic indicators." (PMID 40906676, 2025). "AP-1 is a transcriptional regulator of the pro-inflammatory cytokine, TNF-α, which also has been implicated in breast cancer progression and tumorigenesis." (PMID 40806418, 2025). "In the literature, higher TNFα levels in patients with breast cancer have been associated with greater objective and subjective cognitive impairment." (PMID 38840166, 2024). "Cox regression analysis showed that high expression levels of PARP1 and TNF-α were a risk factor for distant metastasis after breast cancer surgery (RRPARP1 = 4.092, 95% CI 2.475–6.766, P < 0.001; RRTNF-α = 1.825, 95% CI 1.189–2.799, P = 0.006)." (PMID 38388665, 2024). "The data showed that the high serum levels of Groα (≥708 pg/mL), IP10 (≥389), and TNFα (≥21 pg/mL) increased OR for breast cancer risk significantly in both AA and LA and both ages ≤ 50 years and age > 50 years groups." (PMID 38541912, 2024). "For instance, a recent MR finds that lower TNF-a is related to a reduced risk of IHD but an increased risk of breast cancer, mirroring the pattern observed in this MR study." (PMID 39519507, 2024). "TNF-α promotes the expression of carcinogenic CCL5 variants in breast cancer cells, instigating tumor cell detachment and dissemination." (PMID 38347830, 2024).
breast carcinoma (continued). "Gene set enrichment analysis (GSEA) analysis revealed that breast cancer patients in the high-risk group showed a considerably enrichment in myogenesis, TNFα signaling via NF-κB as well as early and late estrogen response." (PMID 37564657, 2023). "The progression of breast cancer is linked to TNF-α, which causes the mesenchyme transition, and the spread and proliferation of the disease." (PMID 37742025, 2023). "In immunotherapy, TNF-α induced mucin 4 expression in HER2-positive breast cancer can cause resistance to trastuzumab." (PMID 37007080, 2023). "RA-associated malignancies include lung cancer, skin cancer, myeloma, non-Hodgkin’s lymphoma and Hodgkin’s disease, lymphoma associated with TNF inhibitors, leukemia, breast cancer, colorectal cancer, and prostate cancer." (PMID 37957703, 2023). "Increased tissue levels of TNF-α observed in breast cancer are also associated with higher-grade tumors, increased risk of metastasis, poor treatment outcomes, and low chance of recovery from the disease." (PMID 36829557, 2023). "Upregulation of the TNF-α was associated with poor quality of life and poor symptomatic scale in breast cancer patients." (PMID 36751235, 2023). "Two SNPs (rs17705608 and rs7309) in the TANK gene have been associated with breast cancer risk, involving TNF-mediated signal transduction." (PMID 37226243, 2023). "Briefly, these results support the reliability and interpretability of our model, suggesting that the model can recognize patients with subtypes of breast cancer that are highly associated with NFκB/TNF genes." (PMID 37475016, 2023). "Conversely, genetic deficiency of TNFα enhanced tumour burden in a mouse model of skin cancer, and in humans elevated TNFα expression is associated with breast cancer recurrence and poor prognosis in ovarian cancer patients." (PMID 37455828, 2023). "Decreased serum levels of TNF-α were also associated with anti-tumor effects in an MCF-7-derived breast cancer in a mouse model treated with the opiate, tramadol, which is associated with reduced mortality in patients." (PMID 38201482, 2023). "A systematic review by Tyagi et al14 presented that IL‐6, IL‐1β, and TNF‐α were associated with cognitive dysfunction in post‐chemotherapy breast cancer patients." (PMID 36965094, 2023). "ProLBS with FOS use decreases pro-inflammatory TNF-α in breast cancer survivors and improves quality of life in those with breast-cancer-associated lymphedema." (PMID 36829557, 2023). "TNF-α-induced inflammation is associated with disease severity and a higher rate of recurrence in breast cancer." (PMID 38201482, 2023). "Our previous studies also demonstrated that CTL inhibits breast cancer cell growth and metastasis by causing ROS-induced cell cycle arrest at the G2/M phase and inhibiting TNFα-induced NF-κB activation in both in vitro and in vivo models." (PMID 36835418, 2023). "The TNF signaling pathway has been confirmed to be intricately associated with various diseases, including prostate cancer, breast cancer, and gastric cancer." (PMID 38239355, 2023). "There were also a large number of values below the LOQ for IL-10 and TNF-α and a significant heterogeneity by menopausal status was observed when we assessed the associations between TNF-α and breast cancer risk among women with quantifiable levels of TNF-α." (PMID 35430795, 2022). "An association of TNF and the Hippo signaling pathway for liver cancer, has also been noted in breast-cancer-cell migration." (PMID 35681583, 2022). "IL-6 (ORper standard deviation (SD) = 1.33 (1.11–1.60)) and TNF-α (ORper SD = 1.32 (1.11–1.58)) were positively associated with breast cancer risk in fully adjusted models." (PMID 35948877, 2022). "Together, LPS-induced regression of breast cancer in vivo when IAP proteins are degraded by an IAP antagonist is mainly caused by its stimulating production of TNFα, which rapidly induces cancer cell apoptosis when IAP proteins are degraded." (PMID 36119107, 2022).
breast carcinoma (continued). "Our results indicated that high levels of IL-19 and TNF-α, linked to clinical disease stage and lymph node metastasis, have an autocrine effect on breast cancer cells and produce a milieu conducive to tumour growth." (PMID 35928364, 2022). "The only prospective study analyzing the association between TNF-α and breast cancer risk in premenopausal women showed a positive association across tertiles of TNF-α (P-trend = 0.02)." (PMID 35948877, 2022). "TNFα-activated NF-κB and ER together potentiate gene expression associated with proliferation, invasion, and metastasis in breast cancer cells." (PMID 35761157, 2022). "While the association with IL-6 was consistent across different breast cancer subtypes and tumor sizes, the association with TNF-α was limited to larger tumors." (PMID 35948877, 2022). "Specifically, we found that elevated plasma IL-6 and TNF-α levels were associated with higher DepS risk, which was consistent with the previous research in breast cancer patients receiving adjuvant therapy." (PMID 36615742, 2022). "In another study, higher levels of depressive symptoms were associated with higher levels of IL-1β, and TNF-α post-surgery in breast cancer patients with a mean age of 50 years." (PMID 35547250, 2022). "In conclusion, this work showed that IL-6 and TNF-α are positively associated with breast cancer in premenopausal women in Latin America." (PMID 35948877, 2022). "The evaluated PD-L1 level was found to be associated with high IFNα2 and TNFα in breast cancer patients." (PMID 35053979, 2022). "Only the EPIC-Varese study also reported results for IL-6 and TNF-α among premenopausal women and noted a higher breast cancer risk with increasing levels of IL-6 [RR1SD = 1.58 (1.02–2.46)] and TNF-α [RR1SD=1.81 (0.91–3.61)]." (PMID 35430795, 2022). "Our present experiments show that an AWP1 deficiency induces EMT gene expression and breast cancer cell migration, indicative of an aggressive tumor phenotype, which is mediated by Nox1-ROS-NF-κB-linked signal activation via TNF-α stimulation." (PMID 33816268, 2021). "Since elevated TNF-α in aggressive breast cancers has been linked to lymph node metastasis, it is believed that the elevation of TNF-α is associated with aggressive clinical behavior and a poorer prognosis in malignant cancers." (PMID 33816268, 2021). "High expression and increased serum level of harmful pro-inflammatory cytokines including resistin, TNF-α, IL-6, and IL-8 are associated with shorter survival and poor prognosis of breast cancer." (PMID 33517609, 2021). "An IL-10-secreting B cell named Breg promoted metastasis of breast cancer and it has been shown to be implicated in inflammation-induced squamous cell carcinoma through the secretion of TNF-α in animal models." (PMID 34122412, 2021). "In this study, we examined five cancer immunity-related pathways (IFNα, IFNγ, STAT3, TGFβ and TNFα) in four large independent breast cancer cohorts (n = 6,381) and their associations with the prognosis of breast cancer subtypes." (PMID 33767579, 2021). "It was found that the most increasing parameters of breast cancer risk were high levels of NF-κB, TNF-α, IL-6, PCT, PTX-3, and CRP." (PMID 33776564, 2021). "In overweight and obese individual’s clinical trials, it has been reported that an increased level of TNF-α expression was associated with the increased risk of breast cancer." (PMID 33517609, 2021). "TNF-α signaling has been associated previously with aggressive breast cancer cells and in the promotion of chemotactic migration through ROS generation." (PMID 33816268, 2021).
breast carcinoma (continued). "It is well known that tumor necrosis factor alpha (TNFα) participates as a proinflammatory cytokine, increasing the risk of several cancers, such as colorectal, esophageal, pancreatic, liver, and breast cancer." (PMID 33540543, 2021). "TNFα has been identified as the cytokine present in tumor-conditioned medium from B16 melanoma cells and 4T1 breast cancer cells that causes upregulation of PD-L1 in monocytes." (PMID 33540543, 2021). "A study on Tunisian population demonstrated a positive association between the TNF-α (-308 G/A) polymorphism and breast cancer susceptibility." (PMID 34900737, 2021). "Cytokines such as IL-1β and tumor necrosis factor α have also been linked to the risk and prognosis of breast cancer." (PMID 33962395, 2021). "The findings of our study were equivalent to those reported by other researchers who demonstrated the association of the TNF- α 308 gene polymorphism with breast cancer." (PMID 32102503, 2020). "In contrast, a study on Tunisian population demonstrated a positive association between the TNF-α (-308 G/A) polymorphism and breast cancer susceptibility." (PMID 32102503, 2020). "It is well established that localized TNFα in the tumor microenvironment promotes inflammation-associated tumors in most solid tumors, including breast cancer." (PMID 33053908, 2020). "Some KEGG signaling pathways (IL17, TNF, Chemokines, ErbB) as well as cancer-associated pathways (Proteoglycans in cancer, Pathways in cancer, Bladder cancer, Breast cancer, Basal cell carcinoma) were enriched after 4 h EGF treatment." (PMID 33115415, 2020). "Recently a study conducted on USA population reported that TNF-α 308G/A polymorphism was associated with reduced breast-cancer-specific and all-cause mortality." (PMID 32102503, 2020). "TNF-α is a well-documented pro-inflammatory cytokine that is up-regulated in breast cancer, and high levels of TNF-α are associated with breast cancer recurrence." (PMID 32019974, 2020). "Genetically higher TNF levels were associated with higher odds of coronary artery disease and ischaemic stroke and lower odds of overall, colorectal, and breast cancer." (PMID 32805626, 2020). "TNFα is produced by adipocytes, tumor cells, and tumor-associated fibroblasts, and plays a critical role in the development of breast cancer, including cancer cell proliferation, invasion, metastasis, and angiogenesis." (PMID 33053908, 2020). "Accordingly, our findings revealed an association between cats with mammary carcinoma and higher serum levels of two pro-inflammatory cytokines (TNF-α and IL-6), positively correlated with serum CTLA-4 levels, as reported in humans and mice." (PMID 32123292, 2020). "Our results suggest that TNF-α-308G/A polymorphism showed significant association with breast cancer patients." (PMID 32102503, 2020). "TNFα, IL-6, and IL-1β are all elevated in obese breast cancer patients and are associated with breast cancer progression and outcomes." (PMID 32630445, 2020). "Significant association was observed in A allele of TNF-α -308 G/A in breast cancer patients as compared to healthy controls (p<0.0001)." (PMID 32102503, 2020). "A high level of TNFα is characteristic to breast cancer and has frequently been associated with a poor prognosis and an aggressive behavior." (PMID 33187552, 2020). "Among malignancies the association of cytokine genes and breast cancer are the best studied and the association of TNF polymorphisms has received special interest." (PMID 32102503, 2020). "Numerous studies have explored the association of TNF and its receptors in breast cancer progression as well as the therapeutic possibilities." (PMID 31239840, 2019). "Higher concentrations of many inflammatory markers, including CRP, IL-1β, IL-6, and TNF-a, have been linked with a higher risk of breast cancer through the stimulation of angiogenesis, proliferation, migration, metastasis, and prevention of apoptosis." (PMID 31430979, 2019).
breast carcinoma (continued). "Few Latin American studies tested the association between genes in inflammation and energy balance pathways and breast cancer risk (TNF-α, RETN, CAP1, and PTGS2 genes)." (PMID 30781715, 2019). "ER-positive breast cancer cells that resist TNF-α-induced death are associated with a multidrug-resistant phenotype by epithelial-mesenchymal transition- (EMT-) driven mechanisms." (PMID 31485295, 2019). "From the gene coexpression network of BRCA, we see some breast cancer associated genes are isolated, such as ‘TNF’, ‘CD55’, ‘IL1A’." (PMID 29671401, 2018). "Recently, it was revealed that proinflammatory cytokines in serum, such as IL-6, IL-8, and TNF-α, are associated with clinical stage and lymph node metastasis in breast cancer patients." (PMID 30034291, 2018). "Previous studies have consistently reported that TNF-α were positively associated with a larger tumor size and presence of lymph node metastasis in patients with breast cancer." (PMID 30111758, 2018). "TNF-α, a cytokine produced primarily by macrophages and monocytes has been implicated in the progression of breast cancer and promotion of tumor growth by increasing estrogen production." (PMID 30497427, 2018). "Cyclooxygenase-2 (COX-2) expression in breast tumor tissue has been associated with poor breast cancer prognosis as well as high serum TNF-α and TGF-β levels." (PMID 30497427, 2018). "Mortality associated with breast cancer is attributable to aggressive metastasis, to which TNFα plays a central orchestrating role." (PMID 28441391, 2017). "The higher expression of TNF-α in inflammatory breast carcinoma was found to be associated with increasing tumour grade and the metastatic behavior of breast carcinomas." (PMID 28479926, 2017). "Decreased concentrations of adiponectin, and increased concentrations of leptin, IL-6, IL-8, TNF-α, resistin and visfatin were significantly associated with risk of breast cancer." (PMID 29088874, 2017). "We also found that decreased circulating adiponectin levels and increased leptin, IL-6, IL-8, TNF-α, resistin and visfatin levels are significantly associated with risk of breast cancer." (PMID 29088874, 2017). "Then, we found that the expression levels of TNF-α were positively associated with those of HBXIP in clinical breast cancer tissues." (PMID 28938560, 2017). "Data from patients with breast cancer suggest that IL-1β, IL-6, IL-8 and TNF-α contribute to chemotherapy-associated cognitive impairment." (PMID 28542626, 2017). "The protumorigenic activity of TNF also extends to the luminal subtypes, and elevated TNF levels are associated with increased lymph node metastasis and advanced breast cancer stage." (PMID 28607534, 2017). "In conclusion, we reported that TNFα-IKK-YAP/TEAD/p65-HK2 signaling axis mediates TNFα- or macrophage-associated pro-migration of breast cancer cells." (PMID 28945218, 2017). "We then assessed their response to selected cytokines such as insulin growth factor 1 (IGF1) and tumor necrosis factor alpha (TNFα), which are associated with breast cancer risk." (PMID 28369883, 2017). "For example, in a cohort of metastatic breast cancer patients treated with chemotherapy, it was shown that a serum TNF-α concentration > 6.20 pg/ml was associated with 52% less risk of breast cancer progression." (PMID 29202842, 2017). "Among premenopausal women, high TNF-α was associated with significantly increased breast cancer risk in the tertile model only (P trend = 0.017); and high IL-6 was associated with increased risk in the continuous model only (RR 1.58; 95% CI: 1.02–2.46)." (PMID 28983080, 2017). "The aim of this work was to assess the effect of TNF-α on the migration of breast cancer cells and, in addition, to assess its association with the location of membrane-associated proteases in lipid rafts." (PMID 27042827, 2016).